HIF1A (hypoxia inducible factor 1 subunit alpha)
Diseases named in the same sentence as HIF1A in open-access papers (continued):
Sharing a sentence is not in itself a finding about the gene and the disease.
tumor (continued). "Furthermore, lactate accumulation promotes angiogenesis, stabilizes HIF-1α and activates NF-kB and PI-3 kinase signaling in endothelial cells, as well as inducing secretion of the proangiogenic factor VEGF from tumor-associated stromal cells." (PMID 31402913, 2019). "And, hypoxia is a common characteristic in tumor microenvironment and could induce the upregulation of HIF-1α, which induces angiogenesis and also activates many other target genes mediating cell proliferation and apoptosis of cancer." (PMID 31320912, 2019). "Moreover, we find that lung epithelial IKKα functions as a tumor suppressor by reducing both murine NSCLC growth and human NSCLC tumor xenograft burden, at least in part, by inhibiting/repressing HIF-1α protein accumulation and its direct target genes." (PMID 31792060, 2019). "Lactate can also stimulate the stabilization of HIF-1α in aerobic tumor and endothelial cells." (PMID 31788448, 2019). "Moreover, YB‐1‐K81A rescued EwS metastasis to lungs, which correlated with re‐expression of NRF2, G3BP1, and HIF1α in tumor tissues." (PMID 31668005, 2019). "HIF-1α mRNA and protein levels were significantly higher in tumor tissues than in normal tissues." (PMID 31673244, 2019). "Indeed, HIF-1α induces the secretion of stromal cell-derived factor-1 alpha (SDF-1α) by tumor cells in the glioblastoma model, which is a chemokine that potently attracts monocytes/macrophages to promote inflammation, angiogenesis and invasion." (PMID 30708988, 2019). "One study has also reported that haptoglobin could participate with STAT3 and HIF-1a in promoting angiogenesis and cell migration, and thus contributes to driving tumour growth and invasion." (PMID 31042781, 2019). "There are also many new targets for precision therapy, such as Bcl-2 family members, which could increase chemosensitivity of the tumor, and survival protein kinases such as the HIF1a, Src and PI3K pathways." (PMID 30808351, 2019). "HIF1α regulates tumor cell proliferation, invasion, migration, and resistance to radiotherapy." (PMID 31419966, 2019). "In response to hypoxia, tumor cells undergo a metabolic switch and, through the activation of Hypoxia Inducible Factor 1 alpha (HIF1α), shift rapidly toward increased glycolysis and glutaminolysis, and reduced oxidative phosphorylation, for energy production and macromolecular biosynthesis." (PMID 31319613, 2019). "Interestingly, HIF-1α knockout in the pancreas of mouse PDA showed a large increase in the number of B cells in the tumor microenvironment." (PMID 30931508, 2019). "Indeed, the mTOR signaling pathway not only increases HIF-1α synthesis, but also promotes tumor angiogenesis in CRC cells." (PMID 31430901, 2019). "Our findings provide evidence for the first time that IKKα’s mechanism of action as an NSCLC tumor suppressor in lung epithelial cells can be associated with its ability to function as a negative upstream regulator of HIF-1α protein activity." (PMID 31792060, 2019). "Finally, their initial studies showed that though tumor suppressed HIF-1α expression, β-glucan treatment, known to induce HIF-1α successfully abrogated this observed suppression." (PMID 31344853, 2019). "HIF-1α, the principal regulator of hypoxia, mediates a large number of effects in tumor cells." (PMID 31817513, 2019). "Moreover, activation of HIF-1α in the H1437 IKKαKD cells was also correlated with their more robust tumor burden as tumor xenografts compared with IKKαKD H1299 and A549 xenografts." (PMID 31792060, 2019). "In summary, these outcomes imply that prior 2ME + As2O3 treatment attenuates tumour growth efficiently and may suppress OS growth by negatively regulating FoxO1 expression and HIF-1α." (PMID 31905813, 2019).
tumor (continued). "In hypoxic environments, as in tumor tissues, hypoxia-inducible factor 1α (HIF-1α) is commonly induced, which activates both LDH-A, which is one of the LDH isozymes, and pro-angiogenesis factors such as vascular endothelial growth factor (VEGFA, VEGFR) via the same molecular pathway." (PMID 30298469, 2019). "Moreover, the interaction between TSGA10 and HIF-1α can prevent the transcriptional activity of HIF-1α and thus interfere with tumor growth, and angiogenesis." (PMID 31772141, 2019). "Whether experimental, or in spheres or tissue and the distance to the nearest vessel, it affects metabolism in bulk tumor cells and TICs alike, generally via HIF1α." (PMID 31661927, 2019). "In addition to its established roles in EMT and angiogenesis, the effect of miR-200c on HIF-1α strengthens its tumor suppressive activity and therapeutic potential for cancer treatment through the inhibition of hypoxia-induced cellular processes." (PMID 31061665, 2019). "This NEDD4L ubiquitination is affected by hypoxic stress in tumor tissues; therefore, we hypothesized that NEDD4L might be associated with hypoxia-inducible gene HIF-1α." (PMID 31673244, 2019). "Furthermore, in vitro and in vivo studies demonstrated that adaptation to hypoxia is a critical step in tumor progression and it is regulated by HIF-1α." (PMID 31903166, 2019). "Moreover, the expression of HIF-1α was down-regulated in miR-199a mimics transfected cells derived tumours compared with control miRNAs transfection." (PMID 28442599, 2019). "Some studies have concluded that hypoxia-inducible factor-1α (HIF-1α) may play an important role in tumor invasion and metastasis." (PMID 33817155, 2019). "Also, in tumor tissues, depletion of Bclaf1 considerably suppressed the expression of HIF1A, explaining the decrease of VEGFA protein levels." (PMID 30367150, 2019). "Similarly, within the set of M3 tumours, BAP1-negative tumours (n = 27) had a higher expression of HIF1a compared to BAP1-positive tumours (n = 7) (p = 0.015)." (PMID 31323773, 2019). "Few studies have correlated DCE parameters to measures of tumor oxygenation levels such as HIF-1α." (PMID 31437208, 2019). "In addition to angiogenesis, HIF-1α activates glucose metabolism, thereby leading to acidosis in the tumor microenvironment." (PMID 30845711, 2019). "In addition, hypoxia induces upregulation of CTLA-4 and PD-L1 on tumor cells via HIF-1α in several different mouse and human tumor cell lines." (PMID 30930892, 2019). "In addition, the vascular endothelial growth factor (VEGF) and Hypoxia-inducible factor-1α (HIF-1α) expression level in LIH treated tumours was also down-regulated and this state was maintained for several days." (PMID 31671658, 2019). "However, under certain circumstances in tumor, HIF-1α can accumulate under normoxic conditions, promoting angiogenesis and cancer progression." (PMID 30940798, 2019). "Together these results suggest that MEK inhibitors may suppress hypoxia status in CCAs directly via inhibiting HIF-1α expression in CCA cells as well as indirectly via modulating tumor microenvironment." (PMID 30741922, 2019). "Moreover, the role of tumour genetics in expression of HIF1a is more pronounced than the role of tumour size." (PMID 31323773, 2019). "Similarly, in oropharyngeal cancers, patients with an increased expression of HIF-1α in more than 10% of their tumor cells were found to be thrice more likely to fail radiation therapy." (PMID 30754624, 2019). "As already elaborated, HIF-1α can alter carbohydrate metabolism, oxidative stress, expression of cell survival-modulating cytokines, and mediators of drug resistance, enhancing chemosensitivity of tumor cells." (PMID 31333455, 2019). "About this issue, the traditional view is that VEGFA high expression will lead to vascular abnormalities, further aggravation of hypoxia and the activation of HIF-1a pathway in tumor tissues, which could result in increased expression of PD-L1 on tumor cells." (PMID 30972298, 2019).
tumor (continued). "This sensor, which combines a fluorescent far-red protein (mCherry) and the firefly luciferase (FLuc) and is activated by the neoangiogenesis-related transcription factor HIF-1α, allowed us to differentiate tumoural masses with metastatic potential with high accuracy in a mouse model of metastasis." (PMID 31068630, 2019). "In contrast to hypoxic tumor cells, where S1P may be self-sufficient to accumulate HIF-1α the situation in macrophages seems different." (PMID 31379883, 2019). "However, some evidence suggests that the protective effect of hypoxia on radiation damage is at least in part mediated by Hif1α controlled release of proangiogenic and endothelial protective cytokines that restrict radiation damage on the tumor vessels." (PMID 32118030, 2019). "With tumor hypoxia being common in solid tumors, HIF-1α is often constituently expressed." (PMID 31366108, 2019). "In the tumor microenvironment, the presence of oncogenic signals and hypoxic condition activate certain transcription regulators such as hypoxia-inducible factor 1-alpha (HIF-1α) to induce upregulation of VEGF that largely influences tumor vascularization." (PMID 31052558, 2019). "Tumor hypoxia acts as a novel regulator of DNA methylation independently of HIF1A activity." (PMID 30808328, 2019). "HIF1α played a key role in regulating 18F-FDG accumulation of tumor cells." (PMID 31848322, 2019). "The most direct evidence for hypoxia providing a tolerogenic tumor microenvironment for Tregs is the fact that hypoxia-driven HIF-1α strongly increases the expression of forkhead box P3 (Foxp3), which is a distinct marker and a master regulator in the development and function of Tregs." (PMID 30061885, 2018). "However, serum levels of HIF-1α were significantly higher in patients with tumor diameter >5 cm than in patients with tumor diameter <5 cm (P<0.05)." (PMID 29899167, 2018). "Tumor tissue is characterized by low oxygen tension, a condition that promotes the activation and stabilization of hypoxia inducible factor-1α (HIF-1α) which, in turn, controls the transcription of vascular endothelial growth factor (VEGF), thus promoting angiogenesis, tumor growth and metastasis." (PMID 29568362, 2018). "Collectively, elaiophylin might suppress tumor angiogenesis via the downregulation of HIF-1α and VEGF expression." (PMID 29498688, 2018). "Also hypoxia can enhance MDSC migration to the tumor site via HIF-1α-mediated production of chemokines." (PMID 29434587, 2018). "However, serum levels of HIF-1α were significantly higher in patients with tumor diameter >5 cm than in patients with tumor diameter <5 cm." (PMID 29899167, 2018). "Intratumoural hypoxia could induce EMT program in tumor progression, the one important signaling pathway involves HIF-1α and Twist in response to hypoxia." (PMID 30456206, 2018). "Similarly, HIF-1α levels were associated with histological type, metastasis, clinical stage, FIGO stage, and residual tumor." (PMID 29770329, 2018). "Furthermore, recent work by us and two other groups has shown that stress-responsive miR-153 suppresses tumor angiogenesis by inactivating the HIF1α/VEGFA axis under hypoxic conditions." (PMID 29959560, 2018). "The expression of miR-210 is regulated by HIF-1α in a variety of tumor types through binding at the hypoxia responsive element (HRE), and its overexpression has been detected in most solid tumors, its presence being negatively correlated with the clinical outcome." (PMID 29953500, 2018). "HIF1α and HIF2α overexpression were reported in 88 (62%) cases and 1 (1%) tumor, respectively." (PMID 29845746, 2018).
tumor (continued). "Consequently, low-oxygen content in the tumor induces the hypoxia-inducible factor 1 (HIF1A) stabilization." (PMID 30662458, 2018). "Moreover, we show that CoCl2 affects tumor dormancy directly through HIF1α stabilization by investigating effects of CoCl2 on MCF-7 cells containing knockdown of HIF1α expression." (PMID 30127847, 2018). "Moreover, HIF-1α and HIF-2α levels have been observed to accumulate in tumours with FH mutations, implying that the accumulation of fumarate is linked to HIF activation." (PMID 29772792, 2018). "Because the alternation of HIF-1α and DEC expression is closely associated with tumor progression, it would be of interest to examine whether conditional Hif-1α and Dec knockout mice implanted tumor cells affect the circadian rhythm and metabolism." (PMID 29518061, 2018). "In a multivariate Cox’s regression analysis, a low HIF-1α protein and a high EGFR protein level in the tumor were significantly associated with a better prognosis in STS patients compared to the groups II and III that showed similarly poor prognosis (RR = 3.1; p = 0.03 and RR = 3.4; p = 0.048)." (PMID 30513863, 2018). "The detection of tumor hypoxia showed LIH could alleviate tumor hypoxia for two days at least, obviously decreased of HIF-1α and VEGF expression still exist two days post the last injection of LIH." (PMID 29461122, 2018). "PKM2 can drive glycolysis even in absence of oxygen, by promoting the conversion of pyruvate to lactate through a largely unknown mechanism, thus, induction of PKM2 by HIF1α is an adaptation necessary for tumor growth." (PMID 29844464, 2018). "Additionally, it has been reported that herbs can impede tumor angiogenesis by suppressing the HIF-1α-induced expression of VEGF." (PMID 29636781, 2018). "In addition, the in vivo tumor formation rate and tumor growth are also much lower in the psh-HIF-1α cells." (PMID 29587825, 2018). "Finally, it has been demonstrated that, under hypoxia, HIF-1α regulates the switch from the tumor suppressive to the oncogenic function of EZH2." (PMID 30510924, 2018). "The use of anti-vascular drugs as DMXAA in combination with HIF-1α transcription factor inhibitors may supress tumor regrowth." (PMID 29743548, 2018). "Moreover, these cells under IH polarize toward a tumor-promoting phenotype in a HIF1α-dependent manner and influence tumor growth via vascular endothelial growth factor (VEGF)." (PMID 29997451, 2018). "Both hypoxia and IH enhance HIF1α expression, promoting several steps of the metastatic cascade, selecting tumor cell populations and enriching the tumor microenvironment of the primary tumor." (PMID 29997451, 2018). "Additionaly, cell death inhibition by TSA-induced HIF-1α might be associated with various target gene expression such as TGF, EPO and so on to control tumor cell growth and survival." (PMID 29416751, 2018). "The correlations between HIF-1α expression and tumour size as well as tumour stage are debatable." (PMID 29914529, 2018). "We found that COPD-like inflammation and HIF-1α overexpression are each sufficient to potentiate K-ras induced lung tumorigenesis, and that HIF-1α expression in the airway epithelium is required for tumor promotion, increased tumor angiogenesis, and cell proliferation." (PMID 30250643, 2018). "One experiment showed HIF-1α as a tumor suppressor when its inactivation in FSP1-expressing cells in MMTV-PyMT transgenic mice led to enhanced tumor growth by reducing the tumor vascular density with less leaky vessels together with decreased infiltration of TAMs." (PMID 29896451, 2018). "So, the increase in VEGF expression by TSA-induced HIF-1α acetylation could be resulted in promoting blood vessel formation and oxygen supply to increase tumor cell survival." (PMID 29416751, 2018). "Since VEGF transcription is induced by HIF-1α in tumor cells, we also sought to determine whether ALDH1A1 regulates HIF-1α transcriptional activation in MCF-7 cells." (PMID 30541574, 2018).
tumor (continued). "However, the level of HIF-1α in tumor cells in the treatment group significantly decreased, the secretion of TNF-α decreased, and the secretion of IL-4 was significantly increased." (PMID 30185231, 2018). "Moreover, in our study we found a significant correlation between EGFR mRNA and HIF-1α mRNA expression in the tumor tissues as well as in the normal tissues." (PMID 30513863, 2018). "HIF-1α has been shown to work as a tumor promoting factor as well." (PMID 29896451, 2018). "HIF‐1α inhibited the apoptosis of malignant cells, induced γH2AX expression and hypoxic condition, enhanced DNA repair and finally led to the poor response of tumor treatment." (PMID 29860718, 2018). "Nuclear expression of HIF-1α is very high in viable primary tumor tissue." (PMID 30005601, 2018). "A decrease in HIF-1α secondary to tumor reoxygenation resulting from neoadjuvant therapy could produce the observed decreases in CAIX and GLUT1." (PMID 29681762, 2018). "The effect was claimed to be mainly HIF-independent since inactivation of HIF-1α led to increase in the tumor growth, which could be abolished when HIF-1α was inactivated together with PHD2." (PMID 29896451, 2018). "In this regard, we were able to demonstrate that loss of PHD2 in tumor cells leads to decreased tumor growth, depending on an anti-proliferative effect of TGFβ activation through matrix metalloproteinases, but not HIF-1α." (PMID 29434587, 2018). "Macroscopic and microscopic examination of the lungs from CC-LR/HIF-1α Tg mice showed slightly bigger tumors and the development of more papillary-structured advanced and invasive tumor phenotypes with metastatic invasion to the chest wall and intrathoracic lymph nodes (data not shown)." (PMID 30250643, 2018). "Metformin treatment decreased the gene expression of Hif-1α and Socs-3, genes associated with cancer cell resistance to death, in B16F10 cells; these genes have been reported as targets of metformin in different tumor types." (PMID 29899823, 2018). "In support of these proposals, HIF-2α, but not HIF-1α deletion, has been shown to increase tumor growth and progression secondary to loss of the tumor suppressor secretoglobin 3a1 protein in a KRAS-driven lung tumor model." (PMID 29784889, 2018). "Therefore, intracellular iron levels directly regulate HIF-1α stability crucial for the survival and pro-tumor function of TAMs." (PMID 29434587, 2018). "CoCl2 prevents proteasomal degradation of hypoxia-inducible factor-1α (HIF-1α), resulting in a hypoxia-like condition such as might be produced by an in vivo tumor." (PMID 29976150, 2018). "HIF-1α is the most important hypoxia-induced transcription factor and has multiple functions in tumor progression, including changes in the aggressive behavior of the tumor." (PMID 29568752, 2018). "Finally, in contrast to previous reports describing overexpression of HIF2A in both pediatric and adult HGG, only adult GBM possessed HIF2A overexpression in the datasets we analyzed, whereas HIF1A was overexpressed in all three tumor types." (PMID 29164272, 2018). "This study investigated the role played by HIF-1α activity in the susceptibility of GBMs to TMZ treatment, and its role as an early biomarker of tumor response to this drug and has led to us proposing that CMA is the mechanism responsible for modulating such activity." (PMID 30013951, 2018). "As a key regulator, HIF-1α target genes play major roles in critical aspects of tumor biology." (PMID 30315244, 2018). "Furthermore, tumor-derived lactic acid, whose levels are elevated by hypoxic metabolism, promotes M2-like polarization in a HIF-1α-dependent manner." (PMID 30423905, 2018). "The multivariate Cox’s proportional hazards analysis regression model (adjusted for tumor stage, tumor entity, tumor localization, and type of tumor resection) revealed for a higher HIF-1α protein level a trend towards significance for a poor prognosis in STS patients (RR = 1.9; p = 0.09)." (PMID 30513863, 2018).